HAVCR2 (hepatitis A virus cellular receptor 2)
Diseases named in the same sentence as HAVCR2 in open-access papers (continued):
Sharing a sentence is not in itself a finding about the gene and the disease.
tumor (continued). "To investigate the dynamic changes of PDCD1 and HAVCR2 on Treg cells in tumor progression, we analyzed the gene expression on tumor-infiltrated Treg cells in TCGA datasets." (PMID 33936081, 2021). "It has been reported that IL-6 promotes the polarization of monocytes recruited by tumor cells into TAM and the amplification of MDSCs in tumor microenvironment, IL-17 enhanced the expression of PD-1 and HAVCR2 in tumor-infiltrated CD8+ T cells." (PMID 33679751, 2021). "TIM-3, also known as HAVCR2, was predominantly located on NK cells and macrophages, inhibiting the activation of anti-tumor immunity." (PMID 34291083, 2021). "The univariate and multivariate analyses revealed that CTLA4, HAVCR2, age, pTNM stage, and tumor grade were independent factors affecting the prognosis of KIRC patients." (PMID 34336706, 2021). "HAVCR2 (TIM3) of NK interacts with Galectin-9 on tumor cells, dysfunctional CD8 cells, macrophages and dendritic cells in NPC." (PMID 33671917, 2021). "ZDHHC16 expression was significantly positive associated with clinicopathological stage, tumor grade and ICB immunotherapy key genes (i.e., CD274, CTLA4, HAVCR2 and PDCD1, etc.)." (PMID 33794886, 2021). "We found that LGALS9_CD44, MIF_TNFRSF14, CD47_SIRPG, MDK_LRP1 and LGALS9_HAVCR2, CD74_COPA, C3_C3AR1, ANXA1_FPR3 interactions were upregulated in both ductal-tumor and malignant cells versus ductal-normal." (PMID 35087839, 2021). "BTLA and HAVCR2 mediate the inhibition of human tumor specific CD8 + T cells, and CD244 mediates the dysfunction of natural killer cells." (PMID 34512623, 2021). "We found the up-regulation of cytotoxic cells, CD274 (PD-L1), PDCD1, CTLA-4, HAVCR2, IFN-γ, and so on in high-risk group, whereas opposite result was observed only in absolute tumor purity." (PMID 32537435, 2020). "Notably, compared with the PD‐L1− tumor group, the upregulated differentially expressed genes (DEGs) in the CD8‐C2‐Texterm subset from PD‐L1+ tumor group included exhaustion‐related genes such as HAVCR2, CXCL13, PDCD1, TIGIT, LAG3, BATF, GNLY, and CTLA4." (PMID 41194450, 2026). "Interestingly, known markers of activated (TIGIT, LAYN and HAVCR2) and tumor-reactive T cells (ENTPD1) were segregated into different clusters." (PMID 38724668, 2025). "ATC accentuates this pattern: LAG-3, HAVCR2 and TIGIT co-expression defines a terminally dysfunctional CD8/γδ T-cell pool whose clonal diversity contracts in parallel with rising tumour mutational burden, suggesting neo-antigenic pressure but failed immune pruning." (PMID 40959084, 2025). "In the high-risk group, we observed a substantial upregulation of several immune-suppressive and regulatory molecules, including PD-L1 (CD274), CD276, TIM-3 (HAVCR2), LAG3, and TGFB1, all of which are associated with an immunosuppressive tumor microenvironment." (PMID 40959429, 2025). "Besides, in human colorectal cancer cancer cells, mitochondrial dysfunction inhibits the expression of HAVCR-2, thereby affecting the immune escape of tumor cells." (PMID 39184152, 2024). "The expression of HAVCR2 is significantly increased on infiltrating tumor tissues of CD4+ and CD8+ T cells, which may play an important role in progression, invasion, and metastasis." (PMID 39640777, 2024). "T cell Immunoglobulin and Mucin domain 3 (TIM-3), also known as Hepatitis A virus Cellular Receptor 2 (HAVCR2), is another transmembrane protein belonging to the family of immune checkpoint receptors and associated with tumor-mediated immune suppression." (PMID 38893211, 2024). "Interestingly, XBP1 can simultaneously regulate the expression of multiple immune checkpoint molecules, such as PD1, LAG3, and HAVCR2, in some types of tumours, suggesting that XBP1 is a potential target for overcoming immunotherapy resistance." (PMID 38297380, 2024). "Thus, the fact that HAVCR2 induces the EMT pathway indicates that HAVCR2 has a tumor-progressive role." (PMID 39064019, 2024).
tumor (continued). "Importantly, the T‐cell exhaustion biomarkers (LAYN, CTLA4, and HAVCR2) were highly expressed in the tumor tissues." (PMID 38204220, 2024). "Similarly, we found that sTIM3 was significantly elevated in OS patients compared to healthy donors, while HAVCR2 expression was also higher in tumor tissues than normal tissues." (PMID 38730580, 2024). "In addition, mitochondria also participate in the expression of PD-L1 and HAVCR-2 in tumor cells, demonstrating an undeniable role in tumor occurrence and development." (PMID 39184152, 2024). "Several checkpoint and inhibitory receptors, such as PD-1 (gene name: PDCD1), CTLA4, TIM-3 (HAVCR2), LAG3, CD39 (ENTPD1), CD160, KLRG1, CD96, BTLA, 2B4, and TIGIT, have been implicated in the reduction of immune activity and response in the tumor micro-environment." (PMID 39513882, 2024). "HAVCR2/galectin-9 interaction attenuated T-cell expansion and effector function in the tumor microenvironment and chronic infections;Contributes to the formation of tumors through the transformation of cancer cells, regulation of the cell cycle, angiogenesis and cell adhesion." (PMID 36675020, 2023). "We assessed tumor immune microenvironment through the CIBERSORT algorithm, which demonstrated the upregulation of M1 Macrophages and activated DCs and high expression of key immune checkpoint molecules (CTLA4, PDCD1LG2, and HAVCR2) in high-risk group." (PMID 37730669, 2023). "TIM-3, encoded by the HAVCR2 gene, has recently emerged as an immunotherapy target, as it is often co-expressed alongside PD-1 on the most dysfunctional and exhausted population of tumor-infiltrating T-cells." (PMID 37894310, 2023). "However, pro-tumour tissue-resident monocytes demonstrated a consistent increased relative expression of HAVCR2 across all TMEs." (PMID 37696903, 2023). "In addition, the TIM was characterized in terms of the type of tumor‐infiltrating cells, the tumor mutational burden (TMB) together with CLTA4/LAG3/ PD‐L1/HAVCR2/ PD‐1 expression profiles." (PMID 37178411, 2023). "Noticeably, several immune checkpoints were significantly overexpressed in the S-AOIs as compared to E-AOIs, such as the T-cell-specific inhibitory receptor HAVCR2 and its corresponding tumor ligand LGALS9, or the inhibitory CD86 that interacts with CTLA4 on T-cells." (PMID 37460925, 2023). "Besides, TIM-3 (HAVCR2) mediates T cell exhaustion and macrophage activation; Continuous depletion of T cells downregulates the immune response in tumor-carrying hosts." (PMID 34998385, 2022). "In addition, since FREM2 mutation was associated with immune infiltration, we analyzed its association with the expression levels of PDCD1, CD274, CTLA4, LAG3, TIGIT, and HAVCR2, which are important immune checkpoints responsible for tumor immune escape." (PMID 35252356, 2022). "To further investigate the relationship between KIRP tumor immunity, we performed the correlation analysis between KIRP immune checkpoint genes (CTLA4, HAVCR2, PDCD1, PDCD1LG2, and TIGIT) and high mutation frequency genes (TTN, MET, KMT2C, PKHD1, SETD2, and KMT2D)." (PMID 36618928, 2022). "We adopted the algorithm and found that macrophages with high expression levels of LGALS9 could interact with exhausted CD8 T cells expressing high levels of HAVCR2 in tumor tissues in CCAs." (PMID 36531216, 2022). "Furthermore, HAVCR2 overexpression was significantly related to poor survival in all tumor grades, as well as grades II, III, and IV." (PMID 35198632, 2022). "The results of this study were conducive to understanding the functional role of HAVCR2 in the context of tumors and illustrated the potential mechanism of HAVCR2 with tumor–immune interactions, highlighting a potential candidate and biomarker for the immunotherapy revolution in pan-cancer." (PMID 36081997, 2022).
tumor (continued). "The upregulation of Ctla4 and Lag3 was rather specific as no significant changes were observed in mRNA levels of Cd80 and Cd86 (two CTLA4 ligands present in the antigen-presenting (tumour) cells), Tim-3/Galectin-9 (Havcr2/Lgals9), and Pd-l1 (Cd274) immune checkpoints." (PMID 36433941, 2022). "HAVCR2 was highly expressed by both suppressive tumor Tregs and exhausted CD8+ T cells." (PMID 34793335, 2022). "HAVCR2 (encoding TIM3) was one of the main receptors of ex-high T cells, and the IHC results verified that the expression of TIM3 at the protein level was clearly higher in tumor tissues compared with adjacent normal tissues." (PMID 36104333, 2022). "Effector genes such as GZMB, GZMH and KLRG1 were the marker genes in clonotypes shared by all tissues, while the clonotypes present only in tumor showed upregulated T-cell exhaustion genes (HAVCR2, LAG3, CTLA4, TIGIT, PDCD1, and ICOS) and activation genes (SELL and TNFRSF9)." (PMID 36185254, 2022). "Furthermore, mRNA expression studies, demonstrate a negative correlation between DVL-1 expression and the markers for T cell exhaustion (e.g. CTLA4, HAVCR2), CD8+ T cell (CD8B), tumor-associated macrophages (TAM), T helper cell, and dendritic cells." (PMID 34659647, 2021). "Inhibitory immune marker (HAVCR2) and activating immune receptors (CD80, TNFRSF4, and TNFRSF9) were both at higher levels in the high-risk group, suggesting a complex immune microenvironment within the tumor." (PMID 33850474, 2021). "HAVCR2, which also known as TIM3, plays an important role in inhibiting the Th1 response and the expression of cytokines, some preclinical researches have shown that vivo blockade of Tim-3 leading to the enhance of anti-tumor immunity and the inhibition of tumor growth." (PMID 34021184, 2021). "In animal models, combining anti-HAVCR2 and anti-PD-1 has shown to suppress tumor growth." (PMID 34069452, 2021). "Besides, preclinical studies have demonstrated that anti-TIGIT or anti-HAVCR2 can effectively control tumor evolution, suggesting a promising combination target for anti-PD-1/PD-L1 treatment." (PMID 33637086, 2021). "High risk scores correlated significantly negatively with high CTLA-4 and HAVCR2 expression and higher median inhibitory concentration of common anti-tumor chemotherapeutics (e.g., cisplatin, paclitaxel, gemcitabine) and targeted therapy (e.g., erlotinib and gefitinib)." (PMID 34438369, 2021). "The inhibitory receptors PD-1 and CTLA-4 displayed elevated expression on the CD39+ subset, supporting the previous scRNA-seq data, which identified higher expression of genes associated with exhaustion on tumor-infiltrating CD39+ MAIT cells, such as CTLA4 or HAVCR2." (PMID 33205061, 2020). "In this study, we performed a bioinformatics analysis, using the HapMap database, to examine whether the TIM-3/HAVCR2 3′UTR variants are associated with tumorigenesis and tumor progression." (PMID 29796301, 2018). "This association was potentially attributed to MFSD12’s dual roles: promoting tumor cell proliferation, migration, and metastasis while critically modulating the tumor immune microenvironment, particularly through interaction with the HAVCR2/LGALS9 immune checkpoint axis." (PMID 41194934, 2025). "Consequently, among the expressed genes of PBLs at the pre-dose time point, we identified Havcr2 as a gene that could predict complete tumor elimination by treatment with combined DSP-0509 and RT with the highest predictive performance." (PMID 39054418, 2024). "Consequently, HAVCR2 acts as an inhibitor of tumor growth by activating the apoptosis pathway." (PMID 39064019, 2024). "The data suggested that HAVCR2 expression might modulate tumor-infiltrating lymphocytes." (PMID 36081997, 2022).
tumor (continued). "In this study, we also conducted correlational analysis for the two subtypes and the expression of tumor immune checkpoint genes (PD-1, PD-L1, CTLA-4, and HAVCR2), and our results revealed that subtype A was positively associated with the expression of PD-L1, HAVCR2, and CTLA-4." (PMID 35350786, 2022). "The expression of LAG3 and HAVCR2 also exhibited significant positive associations with intratumoral TILs, and immunofluorescence analysis confirmed the higher percentage of LAG-3+ and HAVCR2+ CD8+ T cells in the total CD8+ T cells in tumor epithelial nests compared with those in the tumor stroma." (PMID 32686767, 2020). "However, when looking at the expression level, we observed relatively high expression of LAG3 and HAVCR2 in both primary and recurrent tumor and a trend of greater expression for TIGIT, CTLA4, BTLA, and PDCD1 in recurrent tumor tissue, compared to primary tumor tissue (NS)." (PMID 33352957, 2020). "Consistent with our Visium analysis, Xenium gene expression analysis revealed that Tfh-like cells located near tumor regions were enriched for C06b CD103+ Tfh-like signature genes, including CCL5, CCL4, GZMA, HAVCR2, and CSF1." (PMID 41542042, 2026). "Both HAVCR2 and LGALS9 expression levels were significantly higher in tumor compared to normal tissue." (PMID 41323263, 2025). "The role of CCL2, HAVCR2, and BIRC5 in immune modulation and tumour progression present potential therapeutic targets." (PMID 40683913, 2025). "TIM-3, also known as hepatitis A virus cellular receptor 2 (HAVCR2), is expressed on both tumor and immune cells and acts as an inhibitory receptor that limits effector T cell responses." (PMID 40725830, 2025). "Several transcripts associated with immunological checkpoints, such as SIGLEC15, PDCD1LG2 (PD-L2), TIGIT, PDCD1 (PD-1), CD274 (PD-L1), CTLA4, LAG3, and HAVCR2 (TIM3), play a crucial role in tumor immune evasion." (PMID 40893939, 2025). "T cell Immunoglobulin and Mucin domain 3 (TIM-3), also known as Hepatitis A Virus Cellular Receptor 2 (HAVCR2), is a transmembrane immune checkpoint receptor involved in tumor-driven immune suppression." (PMID 40677703, 2025). "Numerous transcripts related to immunological checkpoints, including SIGLEC15, PDCD1LG2 (PD-L2), TIGIT, PDCD1 (PD-1), CD274 (PD-L1), CTLA4, LAG3, and HAVCR2 (TIM3), are integral to tumor immune evasion mechanisms." (PMID 41194934, 2025). "Tumour-infiltrating lymphocytes (TILs) exhibit elevated expression of exhaustion markers such as PDCD1, LAG3, and HAVCR2, accompanied by reduced effector cytokines, reflecting chronic antigen exposure." (PMID 41179304, 2025). "Our study revealed a correlation between MMP14 expression and various molecules regulating tumor immune cells, including CSF1R, HAVCR2, KDR, PDCD1LG2, TGFB1, CD70, CD86, and CXCL1." (PMID 40352589, 2025). "PSMB9 displayed strong correlations with classical inhibitory molecules such as LAG3, PDCD1, CTLA4, TIGIT, HAVCR2, SLAMF7, and PD-L1 across nearly all tumor types." (PMID 41020834, 2025). "High expression of immune checkpoints, such as PD‐L1 (PDCD1LG2), TIM‐3 (HAVCR2), and CTLA‐4 (CTLA4), mediates inhibitory immune responses, thus facilitating tumor immune evasion." (PMID 40704619, 2025). "CD8+ T cells that exhibited high expression levels of exhaustion gene (HAVCR2, ENTPD1, LAG3, PDCD1, CXCL13, TOX, and GZMB) in the primary tumor were extracted and clustered." (PMID 40364834, 2025). "We show that HAVCR2 + ADAM + myeloid cells have increased transcription of TREM2 and APOE, which have been proposed as pro-tumor macrophage markers." (PMID 39953623, 2025). "The analysis of the gene signature revealed strong positive correlations with multiple immune checkpoints, including HAVCR2, IL10RA, CSF1R, and CD163, suggesting these genes play a role in regulating the immunosuppressive tumor microenvironment." (PMID 40507280, 2025).
tumor (continued). "These nominated clusters upregulated key marker genes of activation, dysfunction, and differentiation that have been used to identify tumor specificity, such as CXCL13, TIGIT, PDCD1 (PD1), ENTPD1 (CD39), TOX, HAVCR2 (TIM-3), and LAG3." (PMID 40848148, 2025). "While comparing between matched and unmatched tumour and normal tissue samples, upregulation of checkpoint receptor genes, notably CD47, CTLA4, HAVCR2, PVRIG, SIGLEC7, and SIGLEC9, were specifically detected in malignant compared to normal tissues." (PMID 39877370, 2024). "Expression of inhibitory receptors (IRs) PD-1, TIM-3 (HAVCR2), and BTLA was significantly higher on CD8+ T cells isolated from tumor microenvironment, which is the major feature of exhaustive T cells." (PMID 38366083, 2024). "We found that it was correlated with tumor immunotherapy targets BTLA, CTLA4, HAVCR2, LAG3, PDCD1, and TIGIT in HNSC; ICOS were all significantly correlated." (PMID 39483471, 2024). "The mRNA expression levels of MDGs in clinical ccRCC tissues were shown to exhibit higher expressions of CD14, ABCG1, TGFA, and HAVCR2 but lower expressions of KITLG and KDF1 in the tumor samples than in the adjacent control samples." (PMID 39169402, 2024). "The results demonstrated a positive correlation between FANCD2 and immune checkpoints in most tumor tissues, including CTLA4, HAVCR2, LAG3, PDCD1, PDCD1LG2, SIGLEC15, TIGIT, and particularly CD274." (PMID 38443946, 2024). "In Community 1-related immune genes, Cdk6 and Havcr2 are robustly expressed in the exhaustive CD8 T cells, playing roles in connecting EMT and tumor immune." (PMID 38331768, 2024). "When we compared tumor Teff 1 with normal Teff 1, we observed an increased level of GNLY, GZMB, and IFNG was accompanied by higher HAVCR2 (TIM-3)." (PMID 39454432, 2024). "Overwhelming evidence indicates that the combination of PD1 with HAVCR2, CTLA4 or TIGIT inhibitors can more effectively improve T-cell function and eliminate tumour cells." (PMID 38297380, 2024). "HAVCR2, often called TIM3, is highly expressed within the TME and correlates with suppression of T-cell responses and T-cell exhaustion, suggesting its role in tumor immunity." (PMID 38228846, 2024). "Low TPS results revealed significantly changed pathways involving tumour–non-cancerous cell interactions, such as PD-L1/PD-1 (CD274 on tumour cells and PDCD1 on T cells) and Galectin-9/TIM-3 (LGALS9 on tumour cells and HAVCR2 on immune cells)." (PMID 39457550, 2024). "Wherein, in BLCA tumor, CSF1R (rho = 0.706), HAVCR2 (rho = 0.686), IL-10 (rho = 0.682), and PDCD1LG2 (rho = 0.753) showed the strongest positive correlation with FAP expression." (PMID 37166418, 2023). "In the field of tumor immunotherapy research, the six immune checkpoints PDCD1, CD274, CTLA-4, LAG-3, TIGIT, and HAVCR2 can inhibit the proliferation, activation and effector functions of T cells, and maintain the immune homeostasis in the body." (PMID 37810780, 2023). "2.The interaction between the immune checkpoint proteins CD24 and LGALS9 in tumor epithelial cells, SIGLEC10 in dendritic cells, SIGLEC10 and HAVCR2 in macrophages increased." (PMID 37671151, 2023). "The expression of HAVCR2, PDCD1LG2 and SIGLEC15 is prominently different in normal and tumor samples." (PMID 37065485, 2023). "HAVCR2 and LAG3 can work synergistically to promote the exhaustion of effector T cells and inhibit anti-tumor function." (PMID 38239349, 2023). "We also compared the differences in expression levels of TEX marker genes (HAVCR2, TIGIT, CTLA4, LAG3, and PD1) and the putative tumor stem cell marker genes (CD44 and PROM1) between high and low TEXSRGs-score groups in clinical tumor samples using qRT-PCR." (PMID 37957420, 2023). "CD44, CD45, and HAVCR2 acted as receptors, indicating an important role of endothelial cell-derived LAGALS9 in the LN metastasis of tumor cells." (PMID 38065972, 2023).